RPE65 (retinoid isomerohydrolase RPE65)
Diseases named in the same sentence as RPE65 in open-access papers (continued):
Sharing a sentence is not in itself a finding about the gene and the disease.
retinal degeneration (continued). "Thus, we concluded that (±)-RPE65-61 is a potent visual cycle modulator and likely possesses a promising therapeutic potential for retinal degeneration." (PMID 36227868, 2022). "In conclusion, the rod dysfunction of fast photoresponse kinetics is present in many animal models of retinal degeneration [RhoG90D/+ mice; RhoP347LorS/+ pigs; Rho+/− mice; and RPE65−/−]." (PMID 33509952, 2021). "Indeed the accumulation of these lipofuscin bisretinoids is dependent on a normal visual cycle, and mice with an impaired visual cycle (Rpe65‐/‐) show less accumulation and are more resistant to light‐induced retinal degeneration." (PMID 33934486, 2021). "This is especially relevant given the approved gene therapy, other on-going gene therapy trials (NCT02781480), and also that all previous RPE65-RD gene therapy trials noted retinal thinning following subretinal injection, which suggested continued retinal degeneration despite intervention." (PMID 32347917, 2020). "In contrast to non-human primates, there are naturally occurring canine models of retinal degeneration, where progressive retinal atrophy secondary to mutations in, for example, RPE65, XLPRA1 or PDE6β genes, displays great phenotypic similarities with equivalent retinal degeneration in humans." (PMID 33262683, 2020). "RPE65−/− mice were employed as a model of retinal degeneration." (PMID 30695025, 2019). "In order to ascertain whether BCAAs can protect photoreceptors at a later stage of retinal degeneration, we used rd12, another mouse model for retinal degeneration, which has a nonsense mutation in the Rpe65 gene." (PMID 29560458, 2018). "Retinal degeneration 12 (rd12) mouse model is an LCA animal model with a nonfunctional RPE65 protein because of a mutation in the RPE65 gene." (PMID 26124962, 2015). "Importantly, our Tulp1 and Rpe65 mutant models exhibit a similar time course of retinal degeneration as Mfrprd6 and show similar OS shortening and disorganization at P14 without a change in ONL thickness." (PMID 25357075, 2014). "Finally, we plan to examine the zinc staining of the Rho and RPE65 KO animals and the efficacy of pyruvate and nicotinamide against rhodopsin RP mutant models of retinal degeneration." (PMID 21179242, 2010). "Additionally, mainly NGC-I mRNA expression was induced during retinal degeneration in Rpe65−/− mice." (PMID 19050768, 2008). "An increased mRNA expression of the genes coding for the extracellular matrix proteins neuroglycan C (NGC), interphotoreceptor matrix proteoglycan 2 (IMPG2), and CD44 antigen (CD44) has been observed during retinal degeneration in mice with a targeted disruption of the Rpe65 gene (Rpe65−/− mouse)." (PMID 19050768, 2008). "In our cohort of patients, we identified siblings with early-onset severe retinal degeneration where genomic studies revealed compound heterozygous variants in RPE65, one a known pathogenic missense variant and the other a novel synonymous variant of uncertain significance." (PMID 34938339, 2021). "RPE65 gene therapy for these predominantly juvenile diseases have shown promising results, but the mechanism of how loss of function of RPE65, the enzyme retinoid isomerohydralase, results in retinal degeneration is not known." (PMID 32455741, 2020). "Consistent with the phenotype observed in the cohort of patients analyzed in this study, the RPE65, LCA5, USH2A, CNGB1, FAM161A, CERKL and GUCY2D genes consisting mutations in 13 of the 26 pedigrees have been implicated in causing recessive non-syndromic retinal degeneration." (PMID 26352687, 2015). "However, continuing retinal degeneration in patients who received RPE65 gene therapy suggests that a combinational therapy may be needed to improve vision and to prevent retinal degeneration." (PMID 24849605, 2014). "None of the pathogenic mutations in genes related to congenital retinoschisis (RS1) or retinal degeneration (USH2A, ABCA4, PDE6A, PDE6B, RPE65, etc.)were detected by targeted exome sequencing or WGS." (PMID 36980859, 2023).
retinal degeneration (continued). "Further, (±)-RPE65-61 also protects retina structure and function from LIRD, suggesting a therapeutic potential for retinal degeneration." (PMID 36227868, 2022). "In eyes with retinal degeneration after the 1.2-mg or 1.0-mg SI injections, RPE and cone and rod photoreceptor cells were decreased in number based on RPE65, PNA, and rhodopsin staining, respectively." (PMID 32107442, 2020). "The ablation of ERK1/2 signaling reduces RPE65 expression levels, leads to decreased retinoid levels, affects the RPE and the retinal structure, and induces retinal degeneration." (PMID 29038159, 2017). "In RPE65- and LRAT-related human RP, there is significant photoreceptor dysfunction and retinal degeneration that ultimately results in legal blindness." (PMID 26656277, 2015). "However, further studies are needed to address in vivo the cytoprotection of α-crystallins against photoreceptor cell death in retinal degeneration, and more specifically to challenge whether they may be efficient to prevent Bax-dependent rod apoptosis in Rpe65-related LCA disease." (PMID 23383327, 2013). "With the exception of a small decrease in RPE65, none of the other profiled proteins reached a statistically significant decrease at this younger age, suggesting that retinal degeneration begins later than P15 in these animals." (PMID 30254279, 2018). "The loss of ERK1/2 activity resulted in a significant decrease in the level of RPE65 expression, a decrease in ocular retinoid levels concomitant with low visual function, and a rapid disorganization of RPE cells, ultimately leading to retinal degeneration." (PMID 29038159, 2017). "By contrast, this treatment induced no retinal degeneration and only a slight ERG loss in Abca4+/+ Rdh8+/+ Rpe65-Leu450 and rd8 background mice." (PMID 27992460, 2016). "The RPE65 protein expression of RPE cells in the kaempferol group got an obvious improvement compared with that of the NaIO3-treated model group; these results suggested that the kaempferol can protect the RPE cells damage induced in sodium iodate-induced retinal degeneration rats." (PMID 30584457, 2018).
retinal disease (48 papers, 2011 to 2026). "For c.200T>A; p.(Leu67Gln), another missense variant at the same codon has been reported repeatedly in the literature and ClinVar in causal relationship with RPE65-related retinal disease." (PMID 40757766, 2025). "Luxturna was approved by the U.S. FDA in 2017 for the treatment of adult and pediatric patients with inherited retinal disease caused by biallelic RPE65 mutations." (PMID 41235102, 2025). "This study underscores the phenotypic variability of RPE65-associated retinal disease and the value of multimodal diagnostics in distinguishing stationary, hypomorphic presentations from progressive forms." (PMID 41251530, 2025). "Even more significant, subretinal injections were applied in approved gene therapies to treat retinal diseases in human, e.g., for RPE65 deficiencies." (PMID 36980294, 2023). "Current studies show that most of the known mutations in the functional region of the RPE65 protein can cause retinal disease." (PMID 37547722, 2023). "Voretigene neparvovec is administered via a single subretinal injection, and uses an adeno-associated viral (AAV) vector serotype 2 (AAV2) to restore a functional copy of the RPE65 gene in patients with biallelic mutations in RPE65 causing retinal disease." (PMID 34950193, 2021). "The importance of RPE65 in visual function is underscored by the finding that more than 100 mutations in RPE65 are associated with retinal diseases." (PMID 32493732, 2021). "The second was Luxturna®, approved in 2018 as the first gene therapy to restore vision in people with rare inherited retinal disease, caused by mutations in the RPE65 gene." (PMID 32587848, 2020). "Both variants have repeatedly been reported in patients with RPE65-related retinal disease." (PMID 40757766, 2025). "Our findings may provide valuable insights for the accurate diagnosis of RPE65-mutated inherited retinal diseases." (PMID 37547722, 2023). "However, predicting the significance of missense variations associated with RPE65-mediated inherited retinal diseases (IRDs) is challenging as both benign and pathogenic variations coexist in almost every disease-associated gene." (PMID 37547722, 2023). "Pathogenic variants in RPE65 lead to retinal diseases, causing a vision impairment." (PMID 36429068, 2022). "The retinoid isomerohydrolase RPE65 has received considerable attention worldwide since a successful clinical gene therapy was approved in 2017 as the first treatment for vision loss associated with RPE65-mediated inherited retinal disease." (PMID 33952291, 2021). "Another downregulated gene associated with retinal disease is Glb1l3 (Galactosidase beta 1 like 3), which has been implicated in age-related metabolic stress and found to be reduced in Rpe65 knockout mice, connecting it to the pathophysiology of Leber congenital amaurosis." (PMID 34404875, 2021). "With the approval of RPE65 gene therapy and the increased number of inherited retinal disease patients undergoing DNA sequencing, there is an increasing need for higher throughput pathogenicity assays for RPE65 variants." (PMID 39975398, 2025). "In this report, we present four patients with mild RPE65-related retinal disease phenotypes who received treatment with voretigene neparvovec in Germany and Belgium." (PMID 40757766, 2025). "First, the sample size is small, primarily due to the extreme rarity of these very mild cases of RPE65-related retinal disease." (PMID 41251530, 2025). "This study aimed to develop a prediction model to classify RPE65-mediated inherited retinal disease (IRDs) based on protein secondary structure and to analyze phenotype-protein structure correlations of RPE65 missense variants in a Chinese cohort." (PMID 37547722, 2023). "The RPE65 (HGNC: 10294; NM_000329.2) gene was one of the first RPE-expressed genes discovered to be associated with retinal disease." (PMID 36429068, 2022).
retinal disease (continued). "RPE65 gene augmentation is the first gene replacement therapy for retinal disease in clinical use and is a landmark step in genomic and precision medical advancement." (PMID 34938339, 2021). "Luxturna, the first ocular gene therapy approved by the FDA, is for biallelic RPE65 retinal disease." (PMID 31963381, 2020). "Subsequent clinical work confirmed a diagnosis of RPE65-RP, making this was a very unusual case of two rare, genetically distinct Mendelian retinal diseases segregating within the same pedigree." (PMID 27624628, 2016). "Inherited retinal disease can also result from a primary dysfunction of the retinal pigment epithelium (RPE) of which RPE65- or BEST1-mutant dogs are examples." (PMID 25198798, 2014). "Because the affected dogs did not share common alleles, we excluded single, fully penetrant mutations in six known canine retinal disease genes: BEST1, PDE6B and PDE6A, RPE65, NPHP4, and CNGB3." (PMID 25198798, 2014). "This phenotype represents the mildest spectrum of RPE65-related retinal disease." (PMID 41251530, 2025). "High-profile approvals of gene therapies for pediatric-onset diseases like spinal muscular atrophy and RPE65-related retinal disease could potentially pave the way for gene therapies as a model for both therapeutic and market viability." (PMID 38403586, 2024). "If atrophic changes were exclusive to gene therapy for RPE65-associated retinal disease, we would expect not to see them in healthy NHP using another AAV vector." (PMID 38881604, 2024). "However, the target population was defined as already having a diagnosis of biallelic RPE65-mediated inherited retinal disease." (PMID 31117188, 2019). "With recent approval of gene replacement therapy Luxturna, for the treatment of RPE65-related retinal disease, the precedence for approval of future gene-based therapies has been set and results of the RPGR early phase clinical trials are awaited with great expectation." (PMID 31487940, 2019). "Deficiency in RPE65 and LRAT causes a spectrum of retinal disease that is typically classified as LCA (LCA2; OMIM #204100) or RP (RP20; OMIM 613794#), but it may include other terms such as early-onset severe rod-cone dystrophy." (PMID 26656277, 2015). "Until now, Rpe65 defection-induced LCA has been most extensively researched retinal disease." (PMID 26062170, 2015). "Gene therapy is an actively evolving approach in the field of inherited retinal diseases, where multiple trials have been launched and completed, leading to the FDA and (voretigene neparvovec) produced by Novartis and Spark Therapeutics Inc. to treat RPE65 deficiency." (PMID 36362067, 2022). "Before gene therapies for retinal disease could be developed, researchers had established animal models in multiple species including rodents and the Briard dogs that led to the understanding of the physiologic role of the RPE65 enzyme in visual function and disease." (PMID 34768969, 2021). "Additionally, while 661W cells express several photoreceptor markers, they do not express all the genes or proteins found in mature photoreceptors, particularly those involved in specific retinal diseases, such as CNGA3 and RPE65." (PMID 40170180, 2025).
retinitis pigmentosa (44 papers, 2012 to 2025). Retinitis pigmentosa (RP) is an inherited retinal dystrophy leading to progressive loss of the photoreceptors and retinal pigment epithelium and resulting in blindness usually after several decades. "Conversely, a D113G mutation within this motif, which is associated with RPE65-associated retinitis pigmentosa, had lesser impact on TnNinaB activity." (PMID 38355721, 2024). "Biallelic mutations in the RPE65 gene affect nearly 8% of Leber Congenital Amaurosis and 2% of Retinitis Pigmentosa cases." (PMID 38627549, 2024). "Retinitis pigmentosa has been linked to both recessive and dominant mutations in RPE65, making heterozygous mutations in the gene less likely to be caused by simple LOF mechanisms." (PMID 37256959, 2023). "The alteration has previously been described in literature compound heterozygous with another variant in RPE65 in association with retinitis pigmentosa in several affected family members (, reported as Glu404 (4-bp ins) (GAG to GCTGGAG))." (PMID 36672611, 2022). "RPE65 is vital for maintaining normal photoceptor function via trans-retinol conversion; mutations or loss of function are associated with retinitis pigmentosa and are implicated in AMD." (PMID 35501923, 2022). "On the other hand, for retinitis pigmentosa associated with the protein deletion type pathology caused by RPE65 gene abnormalities, gene therapy supplementing the wild-type gene was approved by the FDA in 2017, and its effectiveness has been already reported." (PMID 33923985, 2021). "Slc4a4 has also been linked to retinitis pigmentosa (RP) type 17 and Elovl1 is an endogenous inhibitor of the visual cycle enzyme RPE65, defects in which cause RP type 2054–56." (PMID 29116131, 2017). "Mutations in the human RPE65 gene have been linked to retinal degenerative diseases such as Leber congenital amaurosis, retinitis pigmentosa, and childhood onset retinal dystrophy (11, –, 15)." (PMID 24849605, 2014). "Recently, an autosomal dominant mutation in the RPE65 gene has been found in patients with retinitis pigmentosa, suggesting that the mutated allele has a dominant pathogenic effect." (PMID 24849605, 2014). "Further, mutation of the RPE65 gene is the cause of Leber congenital amaurosis Type 2 and retinitis pigmentosa." (PMID 22736942, 2012). "Precise genetic diagnosis in RPE65-mediated retinitis pigmentosa (RP) is necessary to establish eligibility for genetic treatment with voretigene neparvovec: a recombinant adeno-associated viral vector providing a functional RPE65 gene." (PMID 36142423, 2022). "Interestingly, mutations in RPE65 cause retinal pigmentosa similarly to IMPDH1 mutations." (PMID 25714999, 2015). "Affecting approximately 1 in 4000 individuals worldwide, retinitis pigmentosa exhibits significant genetic heterogeneity, with mutations in genes such as RHO, PRPF31, RPE65, USH2A, and NR2E3, which contribute to its diverse clinical presentation." (PMID 40869487, 2025). "The most common diagnoses of biallelic RPE65 mutation-associated IRDs are LCA (LCA2, OMIM # 204100) and retinitis pigmentosa (RP20, OMIM # 613794)." (PMID 38254722, 2024). "Several of these genes were established RPE markers such as RPE65 and BEST1, mutations in both of which can cause retinitis pigmentosa and other retinopathies." (PMID 34200671, 2021). "Evaluating the effectiveness of transplantation can lay the foundation for the development of new treatments for these diseases, including retinitis pigmentosa with RPE-related gene abnormalities (such as RPE65, RDH5, and MERTK), AMD with RPE atrophy." (PMID 33923985, 2021). "Recessive RPE65-associated retinal dystrophy (RPE65-RD) is thought to account for approximately 5% to 10% of LCA and 1% to 2% of retinitis pigmentosa, and successful gene replacement has been demonstrated in phase I/II and III clinical trials." (PMID 32953245, 2020).
retinitis pigmentosa (continued). "RPE65 produces 11-cis retinal and mutations in RPE65 are associated with Leber congenital amaurosis type 2 (LCA2) and retinitis pigmentosa." (PMID 26020955, 2015). "Photoreceptors have been described as degenerated in Rpe65−/− mice and Rpe65 mutant mice like other models of retinitis pigmentosa." (PMID 22736942, 2012). "As a therapeutic drug for retinitis pigmentosa, Luxturna® (voretigene neparvovec) is the only Food and Drug Administration (FDA)-approved retinitis pigmentosa therapy, designated for a small subset of patients with RPE65 mutations." (PMID 36901839, 2023). "Malfunction in secreting RPE65 leads to severe blindness, such as retinitis pigmentosa." (PMID 35742861, 2022). "Among these clinical trials, voretigene neparvovec (Luxturna) that targets RPE65-associated LCA was the first FDA-approved gene therapy drug, while other clinical trials of IRDs, including Retinitis Pigmentosa (RP), Choroideremia and X-linked Retinitis Pigmentosa (XLRP), are also under way." (PMID 33926102, 2021). "However, there is currently only one FDA-approved gene augmentation therapy, Luxturna (voretigene neparvovec-rzyl), available to patients with RPE65-mediated retinitis pigmentosa (RP)." (PMID 34901928, 2021). "Retinoid isomerohydrolase (RPE65) plays a pivotal role in the visual cycle, and functional impairments are known to cause severe forms of inherited retinal degenerations (IRDs), such as Leber congenital amaurosis 2 (LCA2; OMIM#204100) and retinitis pigmentosa (RP; OMIM#613791 and OMIM#618697)." (PMID 40757766, 2025).